Y_RNA (Y RNA )
Gene: Miscellaneous RNA gene on chromosome 2 (85,367,585 to 85,367,686, forward strand). Ensembl gene ENSG00000202382.
Homologues: Orthologues: chimpanzee Y_RNA (100% identical), macaque Y_RNA (96% identical), tropical clawed frog Y_RNA (75% identical). Paralogues in human: RNY3 (91% identical), Y_RNA (90% identical), Y_RNA (89% identical), RNY3P1 (88% identical), Y_RNA (88% identical), Y_RNA (87% identical), Y_RNA (86% identical), Y_RNA (85% identical), RNY3P11 (84% identical), Y_RNA (84% identical), RNY3P14 (83% identical), Y_RNA (83% identical), and 96 more.